Y_RNA (Y RNA )
Gene: Miscellaneous RNA gene on chromosome 6 (30,736,304 to 30,736,414, reverse strand). Ensembl gene ENSG00000201988.
Homologues: Orthologues: chimpanzee Y_RNA (98% identical), macaque Y_RNA (95% identical), guinea pig Y_RNA (90% identical). Paralogues in human: RNY1 (92% identical), Y_RNA (88% identical), Y_RNA (87% identical), RNY1P8 (86% identical), Y_RNA (86% identical), RNY1P11 (86% identical), Y_RNA (85% identical), Y_RNA (84% identical), Y_RNA (83% identical), RNY1P10 (82% identical), RNY1P5 (82% identical), Y_RNA (82% identical), and 98 more.